ABHD5 (abhydrolase domain containing 5, lysophosphatidic acid acyltransferase)
Diseases named in the same sentence as ABHD5 in open-access papers (continued):
Sharing a sentence is not in itself a finding about the gene and the disease.
Hepatic steatosis (14 papers, 2015 to 2025). Steatosis is a term used to denote lipid accumulation within hepatocytes. "Although Abhd5 knock-down caused hepatic steatosis linked to impaired hepatic TAG catabolism and drastically elevated levels of TAGs, DAGs, and ceramides in the liver, the mice did not develop insulin resistance." (PMID 36355098, 2022). "Recently, two groups independently reported that the pathogenesis of hepatic steatosis in carriers of the PNPLA3 (p.Iso148Met) variant is an ABHD5-dependent process." (PMID 36355098, 2022). "In contrast to the wild-type protein, PNPLA3 (I148M) mutant accumulates on the LD, sequesters ABHD5, and causes severe hepatic steatosis in mice and humans." (PMID 32290093, 2020). "Concerning PNPLA3, it has been recently suggested that the I148M variant may be a gain-of-function mutation that promotes hepatic steatosis by accumulating lipid droplets and inhibiting other lipases in an ABHD5-dependent manner." (PMID 40563253, 2025). "While these liver-specific ABHD5-deficient mice similarly developed hepatic steatosis associated with decreased hepatic TAG hydrolase activity and reduced FA oxidation rates, they exhibited plasma TAG concentrations and VLDL production rates comparable to their wild-type littermates." (PMID 36355098, 2022). "Overall, these data suggest that LD targeting of PNPLA3 I148M and the interaction with ABHD5 is required to promote liver steatosis." (PMID 39814233, 2025). "Overall results suggest that the interaction of PNPLA3 I148M with ABHD5 on LD is required to promote liver steatosis." (PMID 39814233, 2025). "Similar to patients, the whole-body knock-out of Abhd5 in mice resulted in systemic TAG accumulation, Jordans’ anomaly, and severe hepatic steatosis, demonstrating the critical role of ABHD5 in ATGL-mediated TAG hydrolysis in vivo." (PMID 36355098, 2022). "Important progress in understanding the ATGL-independent functions of ABHD5 in hepatic lipid and energy metabolism has been made when a PNPLA3 gene variant was associated with the pathogenesis of fatty liver disease in patients." (PMID 36355098, 2022). "Consistent with reduced TAG hydrolase activities, ABHD5-KO mice show significantly increased carcass neutral lipid content with severe hepatic steatosis." (PMID 32290093, 2020). "Moreover, abolishing the LD binding of PNPLA3 I148M prevented the interaction with ABHD5 and liver steatosis." (PMID 39814233, 2025). "The authors demonstrated that the lack of functional ABHD5 causes hepatic steatosis in the presence or absence of ATGL." (PMID 36355098, 2022). "Moreover, viral manipulation of lipid droplet homeostasis via the ABHD5-ATGL axis, akin to natural genetic variation in these proteins, emerges as a possible mechanism by which chronic HCV infection causes liver steatosis." (PMID 32542055, 2020). "Furthermore, as for ABHD5, minor alleles of ATGL associated with human lipid storage diseases do not support HCV production, suggesting a broader overlap between host determinants of liver steatosis and of HCV morphogenesis." (PMID 32542055, 2020). "Furthermore, in the mouse liver, ABHD5 seems to influence the triglyceride metabolism both in an ATGL-dependent and an ATGL-independent manner, and ABHD5 knockdown causes hepatic steatosis even in the genetic absence of ATGL." (PMID 32542055, 2020). "Similar to ABHD5 deficiency, the loss of functional ATGL in humans results in Jordans’ anomaly and systemic TAG accumulation, but less commonly in hepatic steatosis or hepatosplenomegaly, and never in neurological or developmental disorders." (PMID 36355098, 2022).
steatosis (12 papers, 2012 to 2025). Increased lipid within the cytoplasm of cells. "Cardiac-specific ABHD5 deficiency leads to steatosis and heart failure through the inhibition of lipolysis and PPARα-dependent FA oxidation, which provokes endoplasmic reticulum stress and mitochondrial dysfunction." (PMID 36230994, 2022). "Recently, our model in which PNPLA3 I148M sequesters ABHD5 to initiate steatosis was evaluated by the group of Hobbs and Cohen and provided additional evidence that overexpression of ABHD5 can reduce steatosis induced by PNPLA3 I148M." (PMID 39814233, 2025). "Together these data suggest that PNPLA3 I148M targeting and accumulation on LDs is required for initiating steatosis and further support a model by which PNPLA3 I148M sequesters ABHD5 and prevents activation of PNPLA2." (PMID 39814233, 2025). "Importantly, PNPLA3 I148M sequesters ABHD5 away from PNPLA2 leading to steatosis and modifies TAG metabolism in an ABHD5-dependent manner." (PMID 39814233, 2025). "A model that has been proposed that is consistent with the neomorph hypothesis is that PNPLA3-I148M sequesters CGI-58/ABHD5, a cofactor for the triglyceride hydrolase ATGL/PNPLA2, impairing triglyceride hydrolysis on cytosolic lipid droplets (LDs) and thereby driving steatosis." (PMID 38657050, 2024).
colorectal cancer (11 papers, 2016 to 2024). A primary or metastatic malignant neoplasm that affects the colon or rectum. "We and others previously demonstrated that loss of ABHD5 promotes aerobic glycolysis and stimulates migration and invasion of prostate and colorectal cancer cells." (PMID 33219129, 2021). "In colorectal cancer it has been shown that ABHD5 expressed in tumor associated macrophages promote cancer growth." (PMID 28877685, 2017). "Consistent with our findings, a similar association has recently been reported for the ATGL coactivator protein ABHD5 in colorectal cancer, underlining the importance of the regulation of lipolysis in malignant tumors." (PMID 27213586, 2016). "In colorectal cancer patients, higher levels of ABHD5 are associated with better survival rates." (PMID 39328203, 2024). "Therefore, defects in ABHD5 may be associated with the progression of colorectal cancer and its transformation from adenoma to carcinoma." (PMID 39328203, 2024). "ABHD5 plays a pivotal role in enhancing the responsiveness of colorectal cancer to 5-FU by regulating autophagy-related uracil production." (PMID 39328203, 2024). "This research not only offers a new perspective on the role of TAMs in colorectal cancer but also reveals the ABHD5/SRM/polyamine pathway as a potential therapeutic target, opening avenues for novel treatment strategies." (PMID 39328203, 2024). "In Ou’s research, the inhibitory role of ABHD5 in the epithelial−mesenchymal transition (EMT) of colorectal cancer cells was explored." (PMID 39328203, 2024). "In a follow-up study, Miao’s team intriguingly discovered an increase in the expression of ABHD5 within TAMs in colorectal cancer." (PMID 39328203, 2024). "In the ApcMin/+ mouse model, specific deletion of ABHD5 led to an increase in the number and size of tumors in the colon and rectum, indicating that ABHD5 plays a significant role in inhibiting the development of colorectal cancer." (PMID 39328203, 2024). "In summary, the contrasting outcomes regarding ABHD5 in colorectal cancer cells and TAMs suggest that its mechanism of action is subject to multifaceted regulation, which varies depending on specific cellular contexts or environmental conditions." (PMID 39328203, 2024). "ABHD5 has been validated as a tumor suppressor gene in colorectal cancer by multiple laboratories." (PMID 39328203, 2024). "Therefore, the ABHD5/SRM/spermidine metabolic pathway is a novel therapeutic strategy for colorectal cancer treatment." (PMID 37491279, 2023). "Here the authors show that in tumour-associated macrophages ABHD5 inhibits ROS-dependent induction of C/EBPɛ, which transcriptionally activates spermidine synthase, and that blocking ABHD5 delays colorectal cancer growth in mice by inhibiting spermidine production." (PMID 27189574, 2016). "Peng’s study explored how the interaction between ABHD5 and BECN1 regulates autophagy and affects the development of colorectal cancer." (PMID 39328203, 2024). "Clinical data further confirmed a significant correlation between the expression of ABHD5 and the expression of BECN1, LC3-II, and CASP3 in human colorectal cancer tissues." (PMID 39328203, 2024). "In the absence of ABHD5, this interaction is hindered, affecting autophagy-related uracil production and thus increasing the sensitivity of colorectal cancer cells to 5-FU." (PMID 39328203, 2024). "In vitro and in mouse models, macrophage ABHD5 suppressed the expression of C/EBPe in response to reactive oxygen species, inhibiting the generation of spermidine via spermine synthase (SRM), thereby promoting the proliferation of colorectal carcinoma cells." (PMID 39328203, 2024). "Alpha-beta Hydrolase Domain Containing 5 (ABHD5) is a key regulator of intracellular neutral lipids that has been recently identified as a tumor suppressor in colorectal cancer, yet its potential role in PCa has not been investigated." (PMID 29026202, 2017).
colorectal cancer (continued). "Without ABHD5, DPY30 can enter the nucleus, where it promotes the methylation of YAP and histone H3, thereby activating the transcription of c-Met and supporting stem cell survival in colorectal cancer (CRC)." (PMID 39328203, 2024).
lung carcinoma (11 papers, 2020 to 2025). "Thus, we conclude that lung cancer cells secrete exosomal TRIM59 that directly targets ABHD5, leading to ABHD5 deficiency in TAMs." (PMID 32867817, 2020). "The TRIM59-mediated ubiquitination and degradation of abhydrolase-domain-containing 5 (ABHD5) promote lung cancer progression through NLRP3 inflammasome signaling activation and IL-1β production." (PMID 39451518, 2024). "As a downstream target of circ_cMras, ABHD5 may function as an antitumor agent to inhibit lung cancer progression." (PMID 39328203, 2024). "Liang and their colleagues found that cancer-derived exosomal TRIM59 could physically bind with ABHD5, further regulating macrophage and lung cancer progression." (PMID 36591493, 2022). "Tumor-derived exosomal TRIM59 reprograms macrophages toward a tumor-promoting phenotype by inducing the proteasomal degradation of ABHD5, thereby activating the NLRP3 and enhancing lung cancer progression through increased IL-1β secretion." (PMID 40443670, 2025). "In cancer, tumor‐derived exosomal TRIM59 could convert macrophages to a pro‐tumor phenotype via regulating ABHD5 proteasomal degradation, and led to NLRP3 inflammasome activation to promote lung cancer progression." (PMID 40135589, 2025). "Exosomes derived from lung cancer cells secrete TRIM59 and transform macrophages into tumor-promoting macrophages by regulating ABHD5 proteasome degradation, which activates the NLRP3 inflammasome signaling pathway and promotes the progression of lung cancer by secreting IL-1." (PMID 34511114, 2021). "In sum, our results showed that, tumor-derived exosomal TRIM59 converts macrophages to tumor-promoting functions of macrophages via regulating ABHD5 proteasomal degradation, to activate NLRP3 inflammasome signaling pathway to promote lung cancer progression by IL-1β secretion." (PMID 32867817, 2020). "Collectively, these data indicate that tumor-derived exosomal TRIM59 converts macrophages to tumor-promoting functions of macrophages via regulating ABHD5 proteasomal degradation, to activate NLRP3 inflammasome signaling pathway to promote lung cancer progression by IL-1β secretion." (PMID 32867817, 2020). "TRIM59 directly induces the ubiquitination of ABHD5, leading to its proteasome-dependent degradation, activating the NLRP3 inflammasome signaling pathway, and promoting the secretion of IL-1β by macrophages; As the final result, exosomal TRIM59 facilitates lung cancer growth and metastasis." (PMID 35047512, 2021).
Lipid storage disease (10 papers, 2015 to 2025). "Secondly, ABHD5 and ATGL pathogenic variants are both associated with neutral lipid storage diseases affecting multiple organs, but with a different organ spectrum." (PMID 32542055, 2020). "The beginning of the 21st century opened with the discovery of the gene sequences, ABHD5 and PNPLA2, whose mutations cause the onset of the two neutral lipid storage diseases." (PMID 30795549, 2019). "Remarkably, humans and mice with mutant ATGL alleles also suffer from neutral lipid storage disease (OMIM: 610717) but show normal skin development and function, which indicates that ABHD5 exerts an ATGL-independent role in skin physiology." (PMID 30361410, 2018). "Interestingly, minor alleles of ABHD5 and ATGL associated with neutral lipid storage diseases in human, are also impaired in lipid droplet lipolysis and their pro-viral functions." (PMID 32542055, 2020).
Obesity (9 papers, 2016 to 2024). Accumulation of substantial excess body fat. "Another member of the ABHD family, ABHD5, is also considered as a potential therapeutic target for diabetes, obesity, and cardiovascular diseases." (PMID 39619568, 2024). "Regarding lipolytic activities, it was possible to observe that both obesity and exercise groups did not alter the ATGL and ABHD5 levels." (PMID 35484170, 2022).
prostate carcinoma (9 papers, 2017 to 2025). A carcinoma that arises from epithelial cells of the prostate gland. "In prostate cancer, ABHD5 expression is often reduced, and its loss is associated with enhanced lipid accumulation and tumorigenicity." (PMID 41349769, 2025). "To determine the functional significance of ABHD5-mediated c-MYC suppression in prostate cancer cell growth, we examined the proliferative capacity of ABHD5-deficient 22Rv1 cells." (PMID 41349769, 2025). "We found that overexpression of ABHD5 induces cell cycle arrest at the G1 phase and causes growth retardation in a panel of prostate cancer cells." (PMID 33219129, 2021). "This study identifies ABHD5 as a novel suppressor of c-MYC-driven oncogenic signaling in prostate cancer, revealing a previously unrecognized, lipase-independent mechanism underlying its tumor-suppressive activity." (PMID 41349769, 2025). "In this study, we identified ABHD5 as a novel suppressor of c-MYC-driven transcriptional programs in prostate cancer cells through unbiased transcriptomic profiling." (PMID 41349769, 2025). "These insights broaden the functional landscape of ABHD5 and establish a mechanistic connection between lipid metabolic regulators and oncogene control in prostate cancer." (PMID 41349769, 2025). "Here, we identify ABHD5 as a suppressor of c-MYC-driven transcriptional programs in prostate cancer cells." (PMID 41349769, 2025). "Knocking down ABHD5 can promote lipid droplet accumulation and induce death in prostate cancer cells by triggering apoptosis through mechanisms involving the AMPK/P70S6 pathway." (PMID 39328203, 2024). "In prostate cancer, ABHD5 impairs cell proliferation, metastasis and EMT progression via facilitating aerobic glycolysis and inhibiting mitochondrial respiration." (PMID 39093497, 2024). "Chen’s research revealed the role of ABHD5 as a co-factor for lipase, which plays a role in the behavioral patterns and invasiveness of prostate cancer (PCa) cells." (PMID 39328203, 2024). "In contrast, ABHD5 has also been found to have an inhibitory effect on the proliferation and invasion of prostate cancer cells, and they also noted that ABDH5 regulates prostate cancer cells independently of ATGL." (PMID 35912266, 2022). "We also confirmed the potent inhibition of cell proliferation by ABHD5 overexpression in an additional prostate cancer cell line LNCaP cells." (PMID 33219129, 2021). "Our results strongly suggest that inhibition of both DGAT1 and ABHD5 promote prostate cancer cell death." (PMID 28877685, 2017). "Our results indicate that DGAT1, ABHD5, ACAT1 and ATGL are overexpressed in prostate cancer cells compared to PBMCs and of these overexpressed genes, DGAT1 and ABHD5 aid in the growth of the prostate cancer cells." (PMID 28877685, 2017). "As prostate cancer cells overexpress DGAT1 and ABHD5; both can be targeted to block prostate cancer cell growth." (PMID 28877685, 2017). "In summary our findings indicate that inhibition of both DGAT1 and ABHD5 using siRNA leads to reduction in prostate cancer cell growth." (PMID 28877685, 2017). "Because c-MYC amplification drives the development of castration resistance, targeting the ABHD5–c-MYC axis may offer an effective therapeutic approach for advanced prostate cancer." (PMID 41349769, 2025). "We demonstrate that pharmacological activation of ABHD5 with the synthetic ligand SR-3420 robustly suppresses c-MYC protein levels in two castration-resistant prostate cancer models expressing either wild-type or constitutively active, alternatively spliced androgen receptor variants." (PMID 41349769, 2025). "Clarifying both PNPLA2-dependent and -independent roles of ABHD5 in prostate cancer may uncover new insights into how lipid metabolism intersects with oncogenic signaling pathways such as c-MYC." (PMID 41349769, 2025). "We previously showed that ABHD5 exerts strong antiproliferative effects in prostate cancer cells." (PMID 41349769, 2025).
prostate carcinoma (continued). "A study by Mitra revealed that prostate cancer cells overexpress ABHD5." (PMID 39328203, 2024). "The findings regarding the role of ABHD5 in prostate cancer differ between the two research teams." (PMID 39328203, 2024). "Interestingly, DGAT-1 is involved in the synthesis of triacylglycerol where as ABHD5 is a hydrolase and participates in the fatty acid oxidation process, yet inhibition of both enzymes similarly promotes prostate cancer cell death." (PMID 28877685, 2017). "Both DGAT1 and ABHD5 can be selectively targeted to block prostate cancer cell growth." (PMID 28877685, 2017). "Inhibition of either DGAT1 or ABHD5 leads to prostate cancer cell death." (PMID 28877685, 2017). "However, recent studies have suggested a tumor-suppressive role for ABHD5 in various cancers, including prostate cancer, though the molecular mechanisms remain unclear." (PMID 41349769, 2025). "Additionally, this study revealed that both diacylglycerol acyltransferase-1 (DGAT1) and ABHD5 are upregulated in prostate cancer cells, suggesting that inhibiting these two proteins could be novel anticancer approaches." (PMID 39328203, 2024). "We treated 22Rv1 and C4-2 prostate cancer cells with SR3420, a synthetic ligand that activates ABHD5 by releasing it from its intracellular repressors." (PMID 41349769, 2025). "DGAT1, ABHD5, and ATGL are overexpressed in prostate cancer cells compared to peripheral blood mononuclear cells, and inhibition of DGAT1 and ABHD5 was found to lead to prostate cancer cell death." (PMID 35912266, 2022). "Since we observed maximum inhibition of growth with ABHD5 and DGAT1 siRNA we examined the mechanism by which these two genes promote prostate cancer growth." (PMID 28877685, 2017).